USP30 (ubiquitin specific peptidase 30)
Diseases named in the same sentence as USP30 in open-access papers (continued):
Sharing a sentence is not in itself a finding about the gene and the disease.
cancer (continued). "Proteases such as ubiquitin specific peptidase 30 (USP30), presenilin associated rhomboid like (PARL), and HtrA serine peptidase 2 (HTRA2) in the UPRmt can interact with mitophagic regulator PINK1-Parkin, and then inhibit mitophagy and maintain mitochondrial proteostasis in cancers." (PMID 30577555, 2018). "Clinically, USP30 is downregulated in TNBC and cancer stem cells (CSCs), with notably reduced nuclear levels in cancer tissues." (PMID 41306556, 2025). "Within the nucleus, USP30 acts as a tumor suppressor by deubiquitinating LEF1 at K379/K382, disrupting the β‐catenin/LEF1 transcriptional complex and inhibiting cancer stemness, chemoresistance, and metastasis in TNBC." (PMID 41306556, 2025). "Nuclear USP30 acts as a tumor suppressor by inhibiting cancer stemness and chemoresistance in triple‐negative breast cancer (TNBC) cells." (PMID 41306556, 2025). "The regulatory relationships among GNPAT, USP30, and DRP1 were previously reported in cancer." (PMID 40709564, 2025). "In addition, in human osteosarcoma (U2-OS) and human breast cancer (MCF7) cells, USP30 regulates the BAX/BAK-dependent apoptosis and its deletion sensitizes cancer cells to BH3-mimetics which can promote cell apoptosis." (PMID 35308234, 2022). "Future studies could focus on investigating whether USP30 promotes AKT signaling and drug resistance in clinical status and whether this combined therapy works on patient-derived cancer cells and murine models." (PMID 35250566, 2022). "Importantly, USP30 also regulates BAX/BAK-dependent apoptosis, and its depletion sensitizes cancer cells to BH3-mimetics." (PMID 25739811, 2015). "Inhibiting USP30 (e.g., ST-539) may synergize with AKT/mTOR inhibitors in cancer treatment." (PMID 40750884, 2025). "This suggests that targeting USP30-regulated mitophagy could represent a promising therapeutic strategy to reinvigorate exhausted CD8+ T cells, offering potential benefits in the treatment of cancer." (PMID 40815646, 2025).
tumor (10 papers, 2022 to 2026). "Functional assays in TNBC cell lines BT549 and MDA‐MB‐231 demonstrated that USP30 overexpression suppressed tumor‐sphere formation, whereas its depletion enhanced the CSC‐like properties of these cells." (PMID 41306556, 2025). "Quantitative evaluation demonstrated that nuclear USP30 levels were significantly reduced in tumor tissues compared to adjacent normal breast tissues." (PMID 41306556, 2025). "The enhanced nuclear retention of the S104A mutant correlated with more potent inhibition of tumor stem cell spheroid formation compared to WT USP30." (PMID 41306556, 2025). "The S104A mutation exhibits enhanced nuclear localization and shows more potent inhibitory effect on CSCs‐like properties, further supporting the tumor‐suppressive role of nuclear USP30." (PMID 41306556, 2025). "Only WT USP30 significantly inhibited tumor‐sphere formation in MDA‐MB‐231 cells, while both the nuclear‐localization‐deficient NLS2m and catalytic inactive C77S mutants lost this capacity." (PMID 41306556, 2025). "Analysis of tumor-infiltrating lymphocytes (TILs) revealed that USP30 deletion significantly increased the MG+TMRM+ CD8+ T cell population, indicating improved mitochondrial fitness." (PMID 40815646, 2025). "Knockdown of USP30 significantly suppressed the proliferation, invasion and migration abilities of BC cells in vitro and tumour growth in vivo, whereas overexpression of USP30 exhibited the opposite effect." (PMID 38146008, 2024). "USP30 knockout mice had fewer tumor nodules and decreased tumor burden and largely attenuated the lipogenesis, inflammation, and hepatocarcinogenesis." (PMID 35308234, 2022). "Immunohistochemistry analysis confirmed the upregulation of USP30 in tumor tissues and categorized tissues into USP30 high-expression group or USP30 low-expression group." (PMID 36474192, 2022). "Third, whether additional nuclear substrates beyond LEF1 contribute to USP30's tumor suppressive functions warrants systematic identification." (PMID 41306556, 2025). "In vivo experiments showed that knockdown of USP30 inhibited tumour growth." (PMID 38146008, 2024). "Moreover, IKKβ-induced USP30 phosphorylation and stabilization promote tumor growth and development in the dimethylnitrosamine (DEN)-/CCL4-induced model of HCC." (PMID 35308234, 2022). "Through compartment‐specific USP30 mutants, we establish a functional dichotomy: mitochondrial USP30 regulates mitophagy, while nuclear USP30 inhibits WNT signaling to exert anti‐tumor effects." (PMID 41306556, 2025). "Upregulation of USP30 can facilitate this process to promote EMT and facilitate tumour invasion and migration." (PMID 38146008, 2024). "Notably, tumor growth was significantly reduced in USP30CKO mice, suggesting that USP30 deletion in CD8+ T cells enhanced antitumor efficiency." (PMID 40815646, 2025).
neurodegenerative disease (7 papers, 2022 to 2026). A disorder of the central nervous system characterized by gradual and progressive loss of neural tissue and neurologic function. "As research continues to elucidate the complex mechanisms underlying neurodegenerative diseases, the role of USP30 as a negative regulator of mitophagy stands out as a promising target for therapeutic intervention." (PMID 39840724, 2025). "The mitochondria-localized deubiquitinase USP30 regulates mitophagy and mitochondrial homeostasis, playing a significant role in the progression of neurodegenerative diseases." (PMID 41688443, 2026). "As mitochondria and peroxisomes intricately influence each other and contribute to cellular ROS, USP30's control over their turnover aligns with its potential implications in the pathogenesis of neurodegenerative diseases." (PMID 39840724, 2025). "The intricate functions of USP30 in mitochondrial quality control position it as a significant factor in the pathogenesis of neurodegenerative diseases characterized by mitochondrial dysfunction and oxidative stress." (PMID 39840724, 2025). "As the narrative of USP30 inhibitors unfolds, each development, from Aumdubin to the Q14 peptide, contributes to a tapestry of innovation in the fight against neurodegenerative diseases." (PMID 39840724, 2025). "The initiation of clinical trials for MTX325 highlights the immense therapeutic potential of targeting USP30 in neurodegenerative diseases." (PMID 39840724, 2025). "Although the research on USP30 in cardiovascular diseases is relatively limited compared to neurodegenerative diseases and cancer, emerging studies suggest its potential involvement." (PMID 40918504, 2025). "Targeting USP30 with specific inhibitors is a promising avenue to restore mitophagy in conditions characterized by mitochondrial defects, including neurodegenerative diseases." (PMID 39840724, 2025). "The implications of USP30 overexpression in neurodegenerative diseases, including AD and PD, signify its potential as a novel target for therapeutic intervention." (PMID 39840724, 2025). "USP30 inhibition has been suggested as a therapeutic approach to facilitate ubiquitination-driven mitophagy in neurodegenerative diseases." (PMID 38225227, 2024). "The most famous and well-studied physiological function of USP30 is its role in mitophagy and the linkage to neurodegenerative disease." (PMID 35308234, 2022). "Embarking on a journey through the molecular landscape of neurodegenerative diseases, the scientific community has uncovered a beacon of hope in the form of USP30 inhibitors, a class of compounds poised to redefine therapeutic strategies for conditions characterized by mitochondrial dysfunction." (PMID 39840724, 2025). "This promising avenue offers new hope for restoring mitochondrial function in neurodegenerative diseases marked by mitochondrial dysfunction and opens the door to further preclinical and clinical investigations, positioning USP30 inhibitors as exciting candidates for disease‐modifying treatments." (PMID 39840724, 2025). "In the context of neurodegenerative diseases, USP30 is considered a potential therapeutic target." (PMID 40918504, 2025). "Furthermore, as we encapsulate our exploration into the potential of USP30 inhibitors, it is clear that this class of compounds represents a pivotal advancement in the quest for novel treatments of neurodegenerative diseases." (PMID 39840724, 2025). "Consequently, the deubiquitination of MUL1 through innovative USP30 inhibitors emerges could mitigate excessive mitochondrial fusion and reinstate mitophagy in the context of neurodegenerative diseases." (PMID 39840724, 2025). "USP30's involvement in regulating PINK1/Parkin‐dependent mitophagy, polyubiquitination, mitochondrial dynamics and the modulation of neurodegenerative disease progression highlights its significance as a therapeutic target." (PMID 39840724, 2025).
kidney disease (3 papers, 2022 to 2025). "These include compounds targeting the mitochondrial DUB USP30 for kidney disease and PD to elevate mitochondrial quality control, yet how the specific inhibition of USP30 can be facilitated on the molecular level had remained elusive." (PMID 40325251, 2025). "The counter-measure of activating the mitophagy pathway with deubiquitinase (DUB) inhibitors such as USP30 inhibitors is progressing in the clinic for kidney disease and the proof of biology for this target will be tested in these trials." (PMID 35754955, 2022).
cardiovascular diseases (2 papers, 2025). "This enhanced understanding ofthe molecular mechanisms surrounding USP30 inhibition will aid inthe creation of next-generation inhibitors that target neurodegenerativeand cardiovascular diseases." (PMID 39804742, 2025). "As mitochondria play a crucial role in cardiac function, and USP30 is involved in mitochondrial quality control and autophagy regulation, it is possible that dysregulation of USP30 could contribute to cardiovascular diseases." (PMID 40918504, 2025). "However, more research is needed to fully understand the specific mechanisms and significance of USP30 in cardiovascular diseases." (PMID 40918504, 2025).
mitochondrial disease (2 papers, 2024 to 2026). "We investigated whether inhibiting USP30 could enhance mitophagy and reduce mutant mtDNA load in a heteroplasmic mitochondrial disease." (PMID 41587019, 2026).
neurological diseases (2 papers, 2018 to 2021). "Downregulation of the mitochondrial gene deubiquitinase USP30 is reported to enhance degradation of damage mitochondria in human neurons, which is beneficial during neurological disorders." (PMID 29609558, 2018).
infection (1 paper, 2024). The state of being infected such as from the introduction of a foreign agent such as serum, vaccine, antigenic substance or organism. "USP30 is regulated by post-translational modifications and takes an active part in many cellular events such as infection, autophagy, BAX/ bak-dependent apoptosis, and tumorigenesis." (PMID 38364250, 2024).
USP30 also shares sentences with these, for which no sentence is quoted: Parkinson’s (2 papers); acute lung injury (1); acute myeloid leukemia (1); Ataxia (1); cervical cancer (1); glioma (1); Huntington disease (1); Infertility (1); NARP syndrome (1); α-synucleinopathy (1).